FCGR1CP (Fc gamma receptor Ic, pseudogene)
Synonyms: CD64c; FCGR1C; FCRIC; IGFR1; IGFRC
Gene: Transcribed unprocessed pseudogene on chromosome 1 (143,874,793 to 143,883,575, forward strand). Ensembl gene ENSG00000265531.
Diseases named in the same sentence as FCGR1CP in open-access papers:
FCGR1CP is named in the same sentence as 8 diseases in open-access papers, as found by Europe PMC text mining. Sharing a sentence is not in itself a finding about the gene and the disease.
FCGR1CP shares sentences with these, for which no sentence is quoted: autism (1 paper); diabetes (1); dyslexia (1); gastric cancer (1); learning disabilities (1); neurodevelopmental disorder (1); schizophrenia (1); tuberculosis (1).